LGR5 (leucine rich repeat containing G protein-coupled receptor 5)
Diseases named in the same sentence as LGR5 in open-access papers (continued):
Sharing a sentence is not in itself a finding about the gene and the disease.
chronic lung disease (1 paper, 2021). According to the definitions of the American and British Thoracic Societies, including pulmonary functional tests, X-rays, and CT scans for items such as fibrosis, bronchiectasis, bullae, emphysema, nodular or lymphomatous abnormalities. "Dysregulated LGR5 expression influences to reduced WNT-β catenine signalling cascades, which is further linked to chronic lung disease including COPD." (PMID 33407823, 2021). "Some of these genes, such as VAMP3, LGR5, PER3, and SDC1, were found to be involved in the different physiological functions of lung and chronic lung disease." (PMID 33407823, 2021).
chronic lymphocytic leukaemia (1 paper, 2020). "It is a potent inhibitor of epithelial cell, keratinocyte, Lgr5+ liver and intestinal epithelial stem cells and lymphocyte and chronic lymphocytic leukaemia B cell proliferation." (PMID 33271899, 2020).
co-infection (1 paper, 2025). "Moreover, the biomarkers of glandular intrinsic components (TFF1) and tumor-associated genes (VIL1 and Lgr5) were significantly upregulated, providing further evidence that host aberrations and tumor progression are triggered by co-infection of EBV with H. pylori." (PMID 40833108, 2025). "Consistently, the results showed that NGOs displayed a significant upregulation of TFF1, VIL1, and Lgr5 at 24 h after co-infection of H. pylori with EBV and a downregulation of CD44 and Axin 2 compared to the H. pylori or EBV-alone groups." (PMID 40833108, 2025). "We found that the co-infection of H. pylori and EBV induced a significant structural change and upregulated the expression of TFF1, VIL1, and Lgr5 to promote cell proliferation and tissue morphogenesis." (PMID 40833108, 2025). "Using quantitative PCR analysis, the results showed that the expressions of Lgr5 and VIL1 gradually increased, peaking at 48 and 72 h in the co-infection of the EBV and H. pylori groups, respectively." (PMID 40833108, 2025).
dermatofibromas (1 paper, 2016). "LGR5+ cells gave rise to pilomatricomas, while LRIG1+ cells formed trichoadenomas and LGR6+ cells formed infundibular cysts in the HF junctional zone and dermatofibromas in the IFE." (PMID 26771241, 2016). "Oncogenic β-catenin expression in LGR5+ cells led to formation of pilomatricomas, while LRIG1+ cells formed trichoadenomas and LGR6+ cells formed dermatofibromas." (PMID 26771241, 2016).
dyslipidemia (1 paper, 2021). "Additionally, the expression of EPGN, LGR5, NCK1, PGRMC2, and VIP were also comfired at transcriptional using qPCR, indicating that those genes are closely linked to dyslipidemia in OSA." (PMID 34880901, 2021). "We discovered that LGR5 might be the likely target gene for the treatment of dyslipidemia in OSA." (PMID 34880901, 2021).
Familial adenomatous polyposis (1 paper, 2018). Familial adenomatous polyposis (FAP) is characterized by the development of hundreds to thousands of adenomas in the rectum and colon during the second decade of life. "The value of CD44 as an important stem cell marker is also supported by a recent study showing the selective expression of the CD44v isoform in LGR5+ intestinal cells isolated from microadenomas of familial adenomatous polyposis patients." (PMID 29652830, 2018).
GEJ adenocarcinoma (1 paper, 2020). "Careful examination of the cores showed that nuclear Lgr5 expression can be seen in 18/95 cases of gastric/GEJ adenocarcinoma (right)." (PMID 32894084, 2020). "Our results show that Lgr5 expression is dynamic in gastric/GEJ adenocarcinoma and heterogeneous across the several disease attributes." (PMID 32894084, 2020). "When analyzed agnostic to the intrinsic heterogeneity in gastric/GEJ adenocarcinoma, Lgr5 expression does not carry a statistically significant prognostic weight, although some prognostic significance is seen in early stage (I/II) patients." (PMID 32894084, 2020). "While previous studies have focused on non-nuclear Lgr5 expression, nuclear Lgr5 expression has been reported in a subset of stem cells, and we examined nuclear Lgr5 expression in a local cohort of 95 cases of gastric/GEJ adenocarcinoma." (PMID 32894084, 2020).
graft versus host disease (1 paper, 2024). An immune system disorder that occurs after allogeneic hematopoietic stem cell transplant and is a reaction of donor immune cells against host tissues. "Likewise, IL-22 administration increased the recovery of Lgr5+ ISCs and epithelial regeneration in a graft-versus-host disease mice model." (PMID 38262747, 2024).
head and neck cancer (1 paper, 2024). A primary or metastatic malignant neoplasm affecting the head and neck. "Our results concerning the prognostic importance of the splice variant of LGR5 (LGR5Δ5) for specific head and neck cancer (OSCC) patients require two open questions." (PMID 39769183, 2024).
Helicobacter infection (1 paper, 2018). "However, using Lgr5-EGFP-IRES-CreERT mice originally developed by Clevers’ group, the same group demonstrated that Lgr5+ chief cells fail to give rise to metaplasia in the same drugs or Helicobacter infection model." (PMID 30384487, 2018).
hepatitis B (1 paper, 2019).
hereditary mixed polyposis syndrome (1 paper, 2025). "Similarly, overexpression of GREM1 in Hereditary mixed polyposis syndrome (HMPS) leads to the persistence or reacquisition of stem‐cell properties in LGR5‐negative cells outside the stem‐cell niche." (PMID 40434957, 2025).
hypopharyngeal cancer (1 paper, 2022). Carcinoma, predominantly squamous cell, arising from the epithelial cells of the hypopharynx. "LGR5 is expressed differently in different tissues but has not been studied in hypopharyngeal cancer." (PMID 36288272, 2022). "LGR5 expression in different tumors is different while that in hypopharyngeal cancer has not been studied." (PMID 36288272, 2022).
hypopharyngeal squamous cell carcinoma (1 paper, 2022). "It is important to clarify the complex relationship between LGR5/YAP signaling and the development of hypopharyngeal squamous cell carcinoma." (PMID 36288272, 2022).
keloid (1 paper, 2022). An irregularly shaped, elevated mark on the skin caused by deposits of excessive amounts of collagen during wound healing. "In conclusion, we identified four immune signaling molecules associated with keloid (LGR5, PTN, JAG1, and DKK1)." (PMID 35967426, 2022). "In the GSE7890 dataset, DKK1 and PTN were downregulated in keloid, whereas JAG1 and LGR5 were upregulated in keloid." (PMID 35967426, 2022). "We found that the expression of DKK1 and PTN was downregulated, while the expression of JAG1 and LGR5 was upregulated in keloid." (PMID 35967426, 2022). "Through immunohistochemistry staining, we found that the expression of DKK1 and PTN was lower in the keloid, while JAG1 and LGR5 showed a higher expression in the keloid." (PMID 35967426, 2022). "Finally, four genes related to keloid (LGR5, PTN, JAG1, and DKK1) were identified, and we further studied keloid pathogenesis, which may provide new ideas and insights for keloid treatment." (PMID 35967426, 2022). "Through the study of keloid in the immunosuppressive microenvironment, exogenous TGF-β1 was induced and LGR5 was highly expressed, but the specific mechanism was not further confirmed." (PMID 35967426, 2022).
liver cirrhosis (1 paper, 2024). "Additionally, to verify the possible relationship between liver cells expressing leucine-rich repeat-containing G-protein coupled receptor 5 (LGR5) and the process of liver cirrhosis, we measured the mRNA level of gene encoding this protein." (PMID 39125684, 2024). "Additionally, we measured LGR5 gene expression to see if this protein—which is a marker of adult stem cells in various tissues, including the liver—may also influence the process of liver cirrhosis." (PMID 39125684, 2024).
lung adenoma (1 paper, 2021). A benign, well circumscribed epithelial neoplasm that arises from the bronchus or the lung parenchyma. "Wnt signaling was found to be amplified by engaging the leucine-rich repeat-containing G-protein-coupled receptor Lgr5, which is a marker for stem cells in multiple epithelial tissues and can drive lung adenoma progression in mouse model." (PMID 34764257, 2021).
lung disease (1 paper, 2017). "Our identification of the specific Lgr5/6 mesenchymal cellular partnerships with epithelial cells provides new ways to understand the complexity of how different cell types are maintained in the healthy lung and possible mechanisms that likely go awry in lung disease." (PMID 28886383, 2017).
mucinous cystadenoma (1 paper, 2022). A benign or low malignant potential cystic epithelial neoplasm composed of cells which contain intracytoplasmic mucin. "Mucinous cystadenomas also expressed negligible levels of LGR5 (mean ± SD: 1.1 ± 2.6), whereas mucinous borderline tumors showed lightly higher levels of LGR5 (mean ± SD: 13.5 ± 17.7)." (PMID 35778589, 2022).
mucinous tumor (1 paper, 2023). "For 586T2A4 P0 parental s.c. tumors, strong Lgr5 expression was observed in the solid tumor mass region but not in the mucinous tumor." (PMID 37746286, 2023).
necrotizing enterocolitis (1 paper, 2018). Necrotizing enterocolitis (NEC) is a devastating disease that affects mostly the intestine of premature infants. "Furthermore, in a murine model of necrotizing enterocolitis (NEC), RA was able to reduce the severity of NEC by downregulating TLR-4-induction of IL-17 and to improve Tregs numbers and repopulation of LGR5+ intestinal stem cells." (PMID 30134532, 2018).
ovarian endometriosis (1 paper, 2018). A non-neoplastic disorder characterized by the growth of endometrial tissue in the ovaries. "Additionally, DIE ectopic lesions displayed a higher average of LGR5+ cells than ovarian endometriosis." (PMID 30577586, 2018).
pilomatricomas (1 paper, 2016). "Pilomatricomas resulting from Ctnnb1 activation in Lgr5-expressing stem cells were surrounded by an increased density of vimentin+ fibroblasts, while fibroblast density in the rest of the skin was unaffected." (PMID 26771241, 2016). "At 4 weeks, back skin of Lgr5 KI/R26R-tdTomato/Ctnnb1lox(ex3)/+ mutant mice showed comprehensive dermal ECM remodeling and CD44 expression in the lower dermis surrounding the pilomatricomas, while the upper dermis contained only mature collagen." (PMID 26771241, 2016).
polyp (1 paper, 2024). A usually exophytic mass attached to the underlying tissue by a broad base or a thin stalk. "The proportions of LGR5+ stem cells and colonocytes were decreased in polyps compared with normal tissue, while those of early colonocytes and goblet cells were increased in all polyp subtypes, although some polyp subtypes did not have statistically significant results." (PMID 38264936, 2024).
polyposis (1 paper, 2013). "In addition, an increased number of Lgr5+ cells were observed in the normal intestinal tissues of Apc mutant mice and proposed as the cause of more severe polyposis." (PMID 24340024, 2013).
Premature ovarian insufficiency (1 paper, 2021). Amenorrhea due to loss of ovarian function before the age of 40. "It has also been shown that downregulation of CAV-1 gene expression in female ovaries pathway affects the Notch2 signaling and causes a decrease in Leucine-rich repeat containing G protein-coupled receptor 5 (Lgr5) leading to POI (premature ovarian insufficiency)." (PMID 34827207, 2021).
rectal adenocarcinomas (1 paper, 2021). "The current work studied gene expression of 3 CSCs related genes, namely LGR5, HES1, and ATOH1 in rectal adenocarcinomas among young Egyptian patients." (PMID 34582650, 2021).
rectal tumor (1 paper, 2021). "LGR5 median expression level in rectal tumor tissues was significantly higher than paired normal tissues." (PMID 34582650, 2021). "Consequently, stage III rectal tumors showed highly significant overexpression of LGR5 compared to stage II." (PMID 34582650, 2021). "Relative quantitative expression of LGR5, HES1 and ATOH1 in rectal tumor tissues compared to paired non-tumor adjacent tissues revealed significant overexpression of LGR5 and HES1 (p <0.001)." (PMID 34582650, 2021).
Rotavirus infection (1 paper, 2021). Infection with any of the rotaviruses. "In this instance, epithelial-specific deletion of the WNT-ligand secretion mediator, WIs, thwarted the repair process, implicating secreted epithelial-derived WNT ligands in the recruitment of Lgr5+ ISCs post rotavirus infection." (PMID 33673710, 2021). "By contrast, epithelial-derived WNTs have been ascribed an essential role in mobilizing unharmed Lgr5+ ISCs (but not +4/reserve ISCs) to replenish differentiated villus epithelial cells, damaged by rotavirus infection." (PMID 33673710, 2021).
sensorineural hearing loss (1 paper, 2022). "The detailed regulatory effects of these conductive materials on Lgr5+ progenitors’ behavior and their potential in the treatment of sensorineural hearing loss have not been investigated." (PMID 35814013, 2022).
serous carcinomas (1 paper, 2022). "Next, we evaluated LGR5 expression in Inclusion cysts (ICs) (n = 12) because they are common benign lesions in the ovary and are considered a precursor for serous carcinomas." (PMID 35778589, 2022). "Strong stromal LGR5 expression without epithelial LGR5 expression was consistently observed in the path from serous cystadenoma to serous borderline tumor to low grade serous carcinoma (LGSC)." (PMID 35778589, 2022).
serous cystadenoma (1 paper, 2022). A serous neoplasm in which the cysts and papillae are lined by a single layer of cells without atypia, architectural complexity or invasion. "Importantly, we discovered that LGR5 is highly expressed in the normal fallopian tube epithelium and that LGR5 expression in ICs and serous cystadenomas is closely associated with a Müllerian phenotype." (PMID 35778589, 2022).
serous endometrial adenocarcinomas (1 paper, 2021). "The SOX9+LGR5+ signature is stronger in tumors characterized by high copy number (copy-number-high) alterations (Wilcoxon text, P value 6.72 × 10−13), typical of serous endometrial adenocarcinomas and linked with a worse prognosis." (PMID 34857954, 2021).
serous ovarian cancer (1 paper, 2022). "LGR5 is a marker for stem epithelial cells at the surface of the adult ovary and is suspected to play a role in serous ovarian cancer." (PMID 36430923, 2022).
skin papilloma (1 paper, 2019). A benign papillary neoplastic growth on the skin composed of epithelial cells and a fibrous stalk. "In this study, we found that mice with Pten knock out in Lgr5+ HFSCs showed increased incidences of skin papilloma and SCC upon DMBA/TPA induction, while double loss of Pten /CTNNB1(β‐catenin gene) or Pten/TNF in Lgr5+ HFSCs greatly diminished the tumorigenesis." (PMID 31754399, 2019). "Together, these data indicate that Pten knockout in Lgr5+ HFSCs greatly promotes skin papilloma formation." (PMID 31754399, 2019).
ulcers (1 paper, 2024). "The TZ in abnormal pathological remodeling might be provided by cumulative cell proliferation due to Lgr5-maintained stem cell activation to heal severe ulcers in the rectum during an emergency." (PMID 39684417, 2024).
tumor (589 papers, 2008 to 2026). "LGR5 is associated with chemoresistance due to its role in maintaining CSCs, promoting tumor survival pathways, driving drug efflux mechanisms, and enabling interactions with the TME." (PMID 39821694, 2025). "LAPTM4B+ stem‐like cells are closely linked to CRC progression, contributing to tumor stratification through their interplay with LGR5+ stem‐like cells." (PMID 40661135, 2025). "In vivo limiting dilution assay using CD133+/LGR5+ PCSC xenografts demonstrated that GD reduces tumor growth, metastasis, and stemness associated with PCSCs by downregulating the expression of Shh and Gli1." (PMID 41599621, 2025). "High LGR5 expression has been shown to be associated with increased tumor migration in cancers including gastric, CRC, breast, and HCC cancers." (PMID 39821694, 2025). "Recently, a study found that LGR5-marked cells represent an important tumor-initiating cell population, and cancer-associated fibroblasts (CAFs) showed robust effects on tumor-initiating cells marked by LGR5." (PMID 41194856, 2025). "Inducible ablation of LGR5+ cells caused tumor regression; however, LGR5−/KRT20+ cells later re-expressed LGR5 and regenerated the CSC pool, demonstrating bidirectional plasticity." (PMID 41002429, 2025). "Leucine-rich repeat-containing G-protein-coupled receptor 5 (LGR5) is a membrane receptor that is associated with the primary tumor formation and metastasis of cancers in the gastrointestinal system." (PMID 39065640, 2024). "Studies should investigate the mechanism underlying CSCs plasticity and tumor regrowth after depletion of Lgr5+ CSCs." (PMID 39183418, 2024). "Taken together, this newly discovered MACC1—LGR5 association contributes to better understanding of the stemness-tumor progression/metastasis link." (PMID 38339354, 2024). "The similar results of the size and number of organoids formed were significantly increased as compared with LGR5+ cells cultured alone within the transwell system of paracrine signaling between LGR5+ tumor cells and cancer‐associated fibroblasts." (PMID 37578396, 2023). "Lgr5+ stem cells are considered the origin of Apc-deficient tumors and overactivation of the Wnt pathway is key for tumor formation." (PMID 36739585, 2023). "In concurrence, a LET-dependent decrease in LGR5 positive SC in both normal and tumors was observed, which suggests the loss of tumor suppressive effects of LGR5 in 56Fe-induced tumors." (PMID 37686516, 2023). "NEDD4L can also inhibit the expression of various tumor-associated membrane proteins, including LGR5, beta-catenin, and transforming growth-factor beta (TGFβ) receptor." (PMID 37240137, 2023). "Research has further demonstrated that the LGR5 gene plays a role in the process of tumor progression, most likely due to this mutational activation of the Wnt/β-catenin pathway." (PMID 37512045, 2023). "In conclusion, we first revealed that the LGR5 marked tumor cells were closely located adjacent to cancer‐associated fibroblasts in DEN‐induced primary murine liver tumor." (PMID 37578396, 2023). "Surprisingly, stem cell markers and associated WNT signaling genes, including Lgr5, decreased in tumor cells along the treatment timeline in a gradient-like manner; this corresponded with increase in differentiated epithelial genes Krt20 and Krt8." (PMID 35600339, 2022). "In order to determine if LGR5-induced tumor EMT was linked to Hippo system activation, VP was utilized in our investigation as a Hippo signaling pathway inhibitor, utilizing dosages that have been shown to not cause mortality in normally grown FaDu cells." (PMID 36288272, 2022). "In colon cancer, R-SPONDIN/LGR5/RNF43 mutations are linked with the deregulation of WNT leading to tumor development." (PMID 36359888, 2022).